IL11 (interleukin 11)
Diseases named in the same sentence as IL11 in open-access papers (continued):
Sharing a sentence is not in itself a finding about the gene and the disease.
breast cancer (continued). "A role for IL-11 signaling in breast cancer has been less well-described, but elevated levels of IL-11 and IL-11Rα are associated with poor patient outcomes and both IL-11 and IL-6 are associated with breast cancer metastasis into bone." (PMID 32765502, 2020). "The development and survival of osteoclast progenitors were reduced after using an IL-11 neutralizing antibody suggesting that breast cancer cells can promote osteoclastogenesis, at least partially, through IL-11." (PMID 32092997, 2020). "TGF-β from the bone matrix stimulates breast cancer cells to secrete PTHrP and IL-11 and induces bone metastasis." (PMID 32674405, 2020). "IL-11, secreted from the bone-specific metastatic breast cancer cell line (BoM-1833), promotes osteolytic bone metastasis by activating RANKL-independent osteoclastogenesis through the JAK1/STAT3 pathway." (PMID 32674405, 2020). "Breast cancer cells that migrate to bones express cytokines and growth factors such as interleukin (IL)-6, IL-8, IL-11, tumor growth factor (TGF)-β, prostaglandin E, or PTHrP, which can mediate RANKL expression." (PMID 32117996, 2020). "COX2 promotes bone metastasis of breast cancer cells through the upregulation of Interleukin-11 (IL-11)." (PMID 32986377, 2020). "More specifically, IL11 is an osteoclast-mobilizing factor which qualifies breast cancer cells to establish osteolytic metastasis in bone tissue." (PMID 31590218, 2019). "It has been described that melatonin, in co-cultures of human breast cancer cells and 3T3-L1 fibroblasts, decreases the levels of TNFα, IL-11, and IL-6 in the culture media and downregulates TNFα, IL-11, and IL-6 mRNA expression in both types of cells." (PMID 31412584, 2019). "Consistent with previous studies in breast cancer, the induction of IL-11 by TGF-β1 was rapid and significantly elevated, peaking at 2 h." (PMID 31349837, 2019). "Accumulating evidence suggests that Smad4 is required for TGF-β downstream genes, including CTGF and IL-11, which are involved in BM in breast cancer." (PMID 31349837, 2019). "Some cytokines (IL-1, IL-6, IL-11, TGFβ) stimulate, while others (IL-12, IL-18, IFNs) inhibit breast cancer proliferation and/or invasion." (PMID 31557971, 2019). "It has been shown the breast cancer cell line overexpressing IL-11 increases tumor burden and osteolytic lesions in mouse bone metastasis model." (PMID 31040267, 2019). "Induction of IL-11 in metastatic breast cancer cells is controlled by TGF-β in a dose-dependent manner through different signaling pathways, such as SMAD (small mother against decapentaplegic) and p38 MAPK." (PMID 31847214, 2019). "A different signaling pathway can be involved, as the synthesis of IL-11 by breast cancer cells is induced by LPA through a specific PKC delta subtype, in the enhancement of breast cancer cell-mediated OC development." (PMID 31847214, 2019). "Here, we present in vitro and in vivo evidences to clarify the role of interleukin-11 (IL-11) as an essential contributor to breast cancer bone metastasis mediated osteolysis." (PMID 31040267, 2019). "IL-11 and CTGF have both been implicated in BM and are TGF-β1-inducible genes in breast cancer cells." (PMID 31349837, 2019). "Together, these findings demonstrate that IL-11 down-regulation contributes to the function of miR-124 in bone metastasis of breast cancer cells both in vitro and in vivo." (PMID 29343249, 2018). "In particular, metastatic breast cancer cells promote osteoclasts formation and activity by secreting osteolytic interleukins (ILs) such as IL-8 and IL-11,as well as TNFαand matrix metalloproteinases (MMP1, MMP2),which are involved in bone matrix destruction." (PMID 30126457, 2018). "In this study, we clarified the role of cancer cell-derived miR-124 in bone metastases from breast cancer and identified that perturbation of the miR-124/IL-11 regulatory axis contributes to the bone metastasis observed in breast cancer." (PMID 29343249, 2018).
breast cancer (continued). "Consistently, the significant positive correlations of CUL1 mRNA expressions with CXCL8 and IL11 mRNA expressions were observed in TCGA breast cancer dataset which includes 1153 breast cancer patients." (PMID 30578411, 2018). "Decreased miR-124 expression has been reported to be an unfavorable independent prognostic factor for patients with breast cancer, whereas high IL-11 expression correlates with high histological grade and poor survival in breast cancer." (PMID 29343249, 2018). "More importantly, in vitro and in vivo assays demonstrated the active role of IL-11 down-regulation in the breast cancer-derived miR-124-mediated suppression of osteoclastogenesis and bone metastasis." (PMID 29343249, 2018). "IL-11 and its receptor have been indicated in breast cancer development and progression, and in 2006 IL-11 was reported as a predictor of poor prognosis in this type of cancer." (PMID 30109213, 2018). "The involvement of miR-124/IL-11 in the prognosis of breast cancer patients with bone metastasis was determined by Kaplan-Meier analysis." (PMID 29343249, 2018). "The roles of CXCL8 and IL11 in CUL1-regulated breast cancer metastasis were further validated by CXCL8 and IL11 rescue assays." (PMID 30578411, 2018). "Several factors are known to regulate the expression of IL-11 in breast cancer, including Ras oncogene and tumor hypoxia." (PMID 28856117, 2017). "A member of the IL-6 cytokine family, IL-11 has been found to play an oncogenic role in various malignancies, including gastric carcinoma, breast cancer, and hepatocellular carcinoma." (PMID 29100303, 2017). "Expression of IL-11 endows breast cancer cells with the capacity to metastasize, particularly to the bone." (PMID 28856117, 2017). "MCP-1 and IL-11 are stimulators within the development and progression of breast cancer, while IL-6 takes part in survival, proliferation, and cell migration processes." (PMID 28763032, 2017). "Lastly, miR-206/TWF1/MKL1-SRF/IL-11 signaling pathway inhibits breast cancer initiation and progression." (PMID 29162923, 2017). "Breast cancer cells express a number of osteoclast acting factors (PTHrP, IL-11, IL-6, TNFα, M-CSF) to promote RANKL." (PMID 27782035, 2016). "Previous studies confirmed serum IL-11 concentration elevation in patients with PCa, breast cancer and lung cancer." (PMID 27028859, 2016). "Osteoclast activity has also been demonstrated to be stimulated by M-CSF, TNFα and interleukins (IL-8, and IL-11) from breast cancer cells." (PMID 27782035, 2016). "Three miRNAs (miR-204, miR-211, and miR-379) inhibit TGF-β-induced IL-11 production in bone metastatic breast cancer cells." (PMID 26343739, 2015). "Interleukin 11 is an osteoclast-mobilizing factor, which enables breast cancer cells to establish osteolytic metastasis in bone." (PMID 24980816, 2014). "In the context of breast cancer, there is currently one report implicating miR-379 in the regulation of interleukin-11 (IL-11) production in breast cancer cell lines." (PMID 23874748, 2013). "To address the precise role of breast cancer-derived IL-11 in osteoclastogenesis, we determined the effect of breast cancer conditioned media on osteoclast progenitor cells with or without an IL-11 neutralizing antibody." (PMID 23311882, 2013). "It has been shown that breast cancer cell lines produce IL-11 and that forced over-expression in cell lines increases tumor burden and osteolytic lesions in an in vivo bone metastasis model." (PMID 23311882, 2013). "Taken together, these observations support the notion that IL-11 plays an important role in breast cancer-induced osteolysis." (PMID 23311882, 2013). "Breast cancer cells in the bone microenvironment can promote osteoclast formation and activity through factors such as PTHrP and IL11." (PMID 23667544, 2013). "Gibson and Colleagues investigated the effect of IL-11 on ameliorating mucositis in a rat model implanted with syngeneic breast cancer following chemotherapy." (PMID 22973511, 2012).
breast cancer (continued). "Factors such as PTHrP, TGF-β, and IL-11 produced by breast cancer cells favor osteoclast maturation and osteolysis, leading to the release of growth factors that stimulate malignant tumor growth." (PMID 22295244, 2012). "Transforming growth factor β (TGF-β) is released from bone during osteoclastic bone resorption and induces production of osteolytic factors, such as interleukin 11 (IL-11), in breast cancer cells." (PMID 22629385, 2012). "Several studies revealed that TGF-β and its target molecules, such as parathyroid hormone-related protein (PTHrP) and interleukin-11 (IL-11), play critical roles in the development of bone metastasis of breast cancers, which occurs in a Smad-dependent fashion." (PMID 22111550, 2012). "High expression of IL-11 correlates with high histological grade and poor survival in breast cancer." (PMID 22629385, 2012). "We propose that in addition to IHH and OPN, Runx2 mediates stimulation of osteoclast activity by up-regulating the expression of the osteoclastogenic cytokines IL-11 and GM-CSF in metastatic breast cancer cells." (PMID 22032690, 2011). "This analysis identified the osteoclastogenic cytokines IL-11 and granulocyte-macrophage colony-stimulating factor (GM-CSF) as new Runx2/CBFβ targets in breast cancer cells." (PMID 22032690, 2011). "Runx2 and CBFβ are required for the expression of genes that mediate the ability of metastatic breast cancer cells to directly modulate both osteoclast (GM-CSF, IL-11) and osteoblast (sclerostin) function." (PMID 22032690, 2011). "We also identified the osteoclast activators IL-11 and granulocyte-macrophage colony-stimulating factor (GM-CSF) as new target genes of Runx2/CBFβ in metastatic breast cancer cells." (PMID 22032690, 2011). "Potential candidate factors are IL-11 and osteopontin, which were shown to stimulate recruitment and activation of osteoclasts in breast cancer osteolytic metastases, and IL-7 that can stimulate spontaneous osteoclastogenesis in bone metastases." (PMID 17683568, 2007). "Breast cancer cells expressing high levels of IL-11 also exhibit higher rates of bone metastases." (PMID 40584290, 2025). "Notably, studies have identified miR-204, miR-211, and miR-379 as inhibitors of TGF-β-induced IL-11 production in bone metastatic breast cancer cells; these miRNAs directly target IL-11 expression by binding to its 3′UTR." (PMID 41230330, 2025). "IL-11/IL-11Rα is connected to bone metastasis and could potentially predict bone metastases from breast cancer." (PMID 40584290, 2025). "Researchers have proposed that IL-11 is an osteolytic factor in human breast cancer cells." (PMID 40584290, 2025). "IL-1, IL-8, and IL-11 are known to aid in tumor progression in breast cancer." (PMID 38726321, 2024). "Given their critical roles in immune regulation, tumor growth, metastasis, and bone remodeling, interleukins, such as IL-6, IL-8, IL-1β, and IL-11, have been useful in predicting the clinical stage and prognosis of patients with breast cancer which has metastasized to the bone." (PMID 39125732, 2024). "Notably, breast cancer cell lines target osteoblasts to stimulate IL-11 production from osteoblast, further increasing the concentration of IL-11 in the bone microenvironment." (PMID 37199584, 2023). "Here we demonstrated IL11 inhibition by piR-2158 via competing with FOSL1 in breast cancer cells." (PMID 37153732, 2023). "Breast cancer cells with high IL-11 expression also show higher occurrences of bone metastasis." (PMID 37199584, 2023). "In addition, the overexpression of COX-2 enhanced the chemotaxis of breast cancer cells to IL-11, thus up-regulating the bone metastasis of tumor." (PMID 37153547, 2023). "IL-11 is considered as osteolytic factor expressed in human breast cancer cells." (PMID 37199584, 2023). "Further analysis using TCGA database indicated upregulation of IL11 in breast cancer tumors." (PMID 37153732, 2023).
breast cancer (continued). "Thus, breast cancer cells produce IL-11, which in turn stimulates RANKL production in the bone microenvironment." (PMID 37199584, 2023). "Interleukins like IL-6, IL-1, and IL-11, trigger breast cancer (BC) development and invasion." (PMID 37675062, 2023). "Importantly, breast cancer cells expressing miR-124 had significantly lower mRNA and protein levels of IL-11 when compared to control." (PMID 35158995, 2022). "Several miRNAs have been identified that may inhibit IL-11 in bone metastatic breast cancer cells, including miR-204, miR-211, miR-379 and miR-124, raising the possibility of miRNA-mimicking therapeutics to limit bone loss in metastatic breast cancer." (PMID 35053592, 2022). "For example, hsa-miR-204 downregulates IL-11 to inhibit the bone metastasis of breast cancer." (PMID 36712850, 2022). "Besides, it has been determined that parathyroid hormone-related peptide (PTHrP) secreted by breast cancer cells invading the bone induces IL-11 by host osteoblasts that sequentially exerts osteoclastogenic activity through PGE2 increase." (PMID 35163731, 2022). "Despite evidence for the substantial role of IL-11 in inducing STAT3 activity in breast cancer, there is limited research examining how its blockade may be exploited therapeutically." (PMID 35053592, 2022). "The lncRNA-ATB is upregulated by TGF-β to stabilize IL-11 transcripts in hepatocellular cancer cells, and its upregulation is also observed in early metastatic breast cancer cells to promote survival within the metastatic niche via IL-11/STAT3-dependent mechanisms." (PMID 35053592, 2022). "However, many pre-clinical studies have highlighted the potential for such therapies, and a number of clinical trials are currently evaluating safety and efficacy of anti-IL-6/IL-11/STAT3 agents for the treatment of breast cancer." (PMID 35053592, 2022). "Indeed, serum levels of IL-11 and IL-8 are reported to be elevated in patients with breast cancer bone metastases when compared to patients with primary breast cancer." (PMID 33809315, 2021). "This represents an important issue and further studies should be conducted to highlight the possible impact that IL-11 could have on the molecular classification of breast cancer as a prognostic marker." (PMID 34201209, 2021). "Interestingly, in a distinct breast cancer cell cooperation model, sub-clonal expression of IL-11 favors the expansion not only of cells that express it, but also of other cellular sub-clones." (PMID 35096847, 2021). "Besides IL-1, IL-6, IL-8 and IL-11, other ILs have been investigated in the context of breast cancer bone metastasis." (PMID 33809315, 2021). "Moreover, the release of high levels of IL-11 by mammary tumour cells correlates with an elevated possibility to develop bone metastasis." (PMID 34201209, 2021). "Moreover, IL-11 was shown to be responsible for poor prognosis in several cancers (including melanoma) correlated with staging and development of metastases in breast cancer, which correlates with our findings." (PMID 34283046, 2021). "Experimental evidence has shown a possible role of IL-11 in breast cancer bone metastasis." (PMID 34201209, 2021). "The authors demonstrated the important role of COX-2-mediated production of IL-11 in breast cancer cells and hypothesized the importance of this process in the development of osteolytic bone metastases in breast cancer patients." (PMID 34201209, 2021). "Others determined the role of breast cancer-derived IL-11 in osteoclastogenesis." (PMID 33809315, 2021). "Breast cancer cells express IL-11R and secrete IL-11, which in turn stimulates osteoclasts." (PMID 34201209, 2021). "A similar scenario was recently demonstrated in a study of metastatic breast cancer in which IL11-expressing breast cancer cells induced a specific pro-tumoral neutrophil gene signature compared to IL11-null breast tumors which recruited tumor-suppressive neutrophils." (PMID 32114681, 2020).
breast cancer (continued). "Meanwhile, it has been reported that IL‐11 could promote the progression of colorectal cancer, breast cancer and gastric cancer." (PMID 32815653, 2020). "In addition, IL-11 and IL-8, which are secreted by breast cancer cells, change the osseous environment in order to facilitate osteoclast formation and bone colonization." (PMID 32674405, 2020). "Moreover, available evidence indicates that both IL-6 and IL-11 cytokines are produced constitutively at equivalent levels by breast cancer cells." (PMID 31491838, 2019). "In addition, human breast cancer tumors expressing IL-11 have higher rates of bone metastasis occurrences." (PMID 31040267, 2019). "Breast cancer cell is known to produce numerous osteolytic factors including parathyroid hormone-related protein (PTHrP), IL-1, IL-6, IL-8, IL-11, vascular endothelial growth factor (VEGF), connective tissue growth factor (CTGF), matrix metallopeptidase 1 (MMP1), hepatocyte growth factor, etc12–16." (PMID 31040267, 2019). "Additionally, miR-124 negatively regulates IL-11 expression in vitro and in vivo, representing a key pathogenetic process in breast cancer metastasis." (PMID 31847214, 2019). "For paclitaxel resistance, the following miRNAs are relevant, miR-17-5P for the target PTEN in ovarian cancer, miR-30c for the targets VIM, IL-11 in breast cancer, miR-125b for Sema4C and Bak1 in breast cancer, and miR-100 for mTOR, miR-145 for P-gp in ovarian cancer, and miR-181a for PTEN in NSCLC." (PMID 35582143, 2019). "Furthermore, miR-124 expression in metastatic bone tissues is positively correlated and IL-11 is negatively correlated with the time from primary breast cancer surgery to the development of bone metastasis." (PMID 29343249, 2018). "Furthermore, IL-11 expression was negatively correlated to the time from breast cancer surgery to bone metastasis development." (PMID 29343249, 2018). "Therefore, IL-11 dysregulation in breast cancer cells contributes to osteolysis development in multiple ways, although the upstream regulator of IL-11 in tumor cells has yet to be discovered." (PMID 29343249, 2018). "In addition to its well-known roles as a hemopoietic growth factor, IL-11 functions as a prominent pro-tumorigenic cytokine in epithelial cancers such as breast cancer by activating the GP130-Janus kinase signaling cascade." (PMID 29343249, 2018). "In mechanism, the human gene expression profiling was used to determine global transcriptional changes in MDA-MB-231 cells, and we identified autocrine expression of the cytokines CXCL8 and IL11 as the target genes of CUL1 in breast cancer cell migration, invasion, metastasis, and angiogenesis." (PMID 30578411, 2018). "Our data indicated that CXCL8 and IL11 contributed to CUL1-regulated breast cancer metastasis." (PMID 30578411, 2018). "Moreover, a recent study indicated that breast cancer cell-derived IL-11 augments osteoclastogenesis by stimulating the development and/or survival of osteoclast progenitor cells." (PMID 29343249, 2018). "In addition, IL-11 expression in breast cancer tissue correlates with a high histological grade along with poor patient survival." (PMID 30648081, 2018). "Moreover, COX2 was found to mediate the production of interleukin-11 (IL-11), up to a 6-fold increase, in triple negative, ER+, and bone-seeking metastatic breast cancer cells." (PMID 29867053, 2018). "Taken together, our data highlighted that CUL1 regulated EZH2 expression to promote the production of autocrine expression of the autocrine cytokines CXCL8 and IL11, and finally significantly aggravating the breast cancer cell metastasis through the PI3K–AKT–mTOR signaling pathway." (PMID 30578411, 2018). "In the bone microenvironment, TGF-β is released from bone during bone resorption, then it stimulates breast cancer cells to produce osteolytic factors such as interleukin 11(IL-11) to mediate osteolysis by stimulating osteoclast formation and bone resorption activity." (PMID 27438705, 2016).